TF (transferrin)
Diseases named in the same sentence as TF in open-access papers (continued):
Sharing a sentence is not in itself a finding about the gene and the disease.
hemochromatosis (continued). "It was postulated that the increased mean MCV in adults with hemochromatosis is due primarily to the increased uptake of transferrin‐bound iron by immature erythroid cells and consequent increased hemoglobin (Hb) synthesis." (PMID 39866924, 2025). "The level of iron showed normal ferritin (86 μg/L) and saturation of transferrin (28%), eliminating hemochromatosis." (PMID 41356961, 2025). "Literature supports the diagnosis of hemochromatosis when serum ferritin is greater than 200 μg/L in women or 300 μg/L in men or transferrin saturation >45%." (PMID 41341325, 2025). "Hemochromatosis was suspected due to elevated serum ferritin and transferrin saturation levels, and the diagnosis was confirmed by liver biopsy." (PMID 39171001, 2024). "Diagnosis of hemochromatosis is based on clinical evaluation, laboratory findings (elevated serum ferritin and transferrin saturation), imaging studies, and genetic testing." (PMID 39323676, 2024). "In laboratory test results, hemochromatosis was characterized by markedly elevated transferrin saturation and serum ferritin." (PMID 39005658, 2024). "Considering that mild abnormalities in the biochemical liver profile are common in hemochromatosis, patients with an unexplained abnormality in the liver profile should be screened for hemochromatosis with a serum ferritin and transferrin saturation." (PMID 38928368, 2024). "This is achieved by inhibiting ferroptosis through the simultaneous inhibition of hemochromatosis, the initiation of transferrin, and the degradation of ferritin." (PMID 37978208, 2023). "Patients with symptoms, signs, or biochemical abnormalities consistent with hemochromatosis should undergo measurement of serum ferritin concentration and transferrin saturation (HIGH QUALITY of EVIDENCE; STRONG RECOMMENDATION)." (PMID 37067673, 2023). "Non-transferrin-bound iron (NTBI) has been identified in the plasma of patients with chronic iron overload disorders, such as hemochromatosis and thalassemia, in which transferrin saturation is significantly elevated." (PMID 35806040, 2022). "In a genome-wide association study of hemochromatosis patients with HFE p.C282Y homozygosity, TS was significantly associated only with the rs3811647 polymorphism in intron 11 of the transferrin gene (TF, chromosome 3q22.1)." (PMID 35659379, 2022). "On the contrary, when iron is high, such as in hemochromatosis, the liver reduces the production of transferrin to reduce the blood’s TIBC." (PMID 36139084, 2022). "Due to within-person biological variability and diurnal fluctuations of serum iron, some argue that, for the diagnosis of HFE hemochromatosis, the ideal specimen for iron studies is a fasting morning sample of transferrin saturation." (PMID 34067164, 2021). "Her serum ferritin was repetitively found to be high (762 and 674 ng/ml, normal range: 28–365 ng/ml) along with a high transferrin saturation (77.4%) indicative for hemochromatosis." (PMID 32019572, 2020). "Transferrin saturation and serum ferritin are significantly higher in individuals with C282Y homozygous hemochromatosis than other individuals." (PMID 32641120, 2020). "One month later, her transferrin saturation was 40.2%, thereby rendering the diagnosis of hemochromatosis rather unlikely." (PMID 32019572, 2020). "TF and human hemochromatosis (HFE) genes are involved in genetic regulation of maintenance of iron homeostasis." (PMID 32564308, 2020). "Iron circulates in blood exclusively bound to transferrin, unless pathological conditions like hemochromatosis occurs, which will result in the presence of low-molecular-weight forms of non-transferrin bound iron." (PMID 31416268, 2019). "The High FErrum (HFE; HGNC:4886) hemochromatosis gene codes for a MHC class I-type protein involved in iron absorption via regulation of the interaction transferrin-transferrin receptor." (PMID 29518107, 2018).
hemochromatosis (continued). "The second hit involved in the development of iron overload in hemochromatosis results from the appearance of the non-transferrin-bound form of iron (NTBI)." (PMID 30486249, 2018). "In HFE hemochromatosis, iron loading of parenchymal cells is partly due to uptake of non-transferrin-bound iron (NTBI) from plasma." (PMID 28331855, 2017). "High serum ferritin levels and transferrin saturation greater than 45% are highly suggestive of hemochromatosis." (PMID 26136783, 2015). "Transferrin (TF) and hemochromatosis (HFE) are two iron metabolism genes for which functional variants are prevalent in North America." (PMID 25287020, 2014). "Liver TFR2 is considered a sensor of diferric transferrin, possibly in a complex with hemochromatosis protein." (PMID 24847265, 2014). "Human hemochromatosis protein (HFE), the protein incriminated in the pathogenesis of hemochromatosis, competes with transferrin for binding to the receptor, thereby impeding the uptake of iron from transferrin." (PMID 23578325, 2013). "Brain iron homeostasis is regulated by different factors, among which the transferrin (Tf) and the hemochromatosis (HFE) proteins seem to play a key role." (PMID 23935582, 2013). "We herein describe a case of AIH that presented with high ferritin levels and transferrin saturation suggesting a diagnosis of hemochromatosis and needed arduous work-up to arrive at accurate diagnosis of AIH." (PMID 24024049, 2013). "On the basis of findings of high levels of serum ferritin and transferrin saturation, and low intensity of liver parenchyma on magnetic resonance imaging (MRI), we made a diagnosis of hemochromatosis." (PMID 29147365, 2013). "The degree to which transferrin is iron saturated can vary from 25% to 30% in a healthy individual to 100% in patients with hemochromatosis, negating the antimicrobial properties of transferrin-mediated iron sequestration." (PMID 20711357, 2010). "Three specific iron metabolism genes that have variants known to alter protein function are hemochromatosis (HFE), transferrin (TF), and heme oxygenase-1 (HMOX-1)." (PMID 19165391, 2009). "We examined the association between common missense variants in the hemochromatosis (HFE) and transferrin (TF) genes and blood lead levels in 422 Mexican children." (PMID 18795173, 2008). "Previous studies assessing the effects of certain genes encoding proteins involved in iron metabolism, such as hemochromatosis (HFE) and Transferrin (TF) genes, on the onset of AD have been contradictory." (PMID 19090990, 2008). "Mean transferrin saturation, mean serum ferritin concentration, and mean units of phlebotomy to achieve iron depletion were greater in men than women with hemochromatosis." (PMID 16042809, 2005). "Additionally, CMR was also helpful in excluding hemochromatosis in one patient in whom serum transferrin saturations levels were mildly elevated, with HFE testing being indeterminate." (PMID 41177866, 2025). "Through the inhibition of hemochromatosis, initiation of transferrin, degradation of ferritin and activation the antioxidant capacity, DFO protects the structural and functional soundness of the retina by inhibiting ferroptosis in the rat models of retinal I/R injury." (PMID 39539617, 2024). "Interestingly, both patients maintained normal transferrin saturation levels, a finding that distinguishes these cases from classical hemochromatosis." (PMID 39229407, 2024). "Empirically, high values of serum ferritin and elevated transferrin saturation as well as genetic screening may help identify suspected hemochromatosis." (PMID 38928368, 2024). "Deferoxamine protects the structural and functional soundness of the retina by inhibiting ferroptosis through the simultaneous inhibition of hemochromatosis, the initiation of transferrin, and the degradation of ferritin and activating the antioxidant capacity of the System Xc-GSH-GPX4 pathway." (PMID 37978208, 2023).
hemochromatosis (continued). "Other works have reported that genes related to iron metabolism, such as the TF and hemochromatosis (HFE) genes, may explain nearly 40% of the genetic variation in serum transferrin levels." (PMID 35052629, 2022). "Without being exclusive, we propose that the accumulation of Fe heavy isotopes in liver could also be related to the NTBI known to appear in plasma when transferrin saturation increases during hemochromatosis." (PMID 34722560, 2021). "The two groups were compared in terms of the following variables: transferrin saturation, iron concentration, the maximum concentration of ferritin at the diagnosis of hemochromatosis and the concentration of ferritin during bloodlettings and parameters of calcium and phosphate metabolism." (PMID 34573286, 2021). "Male HFE hemochromatosis patients with ferritin >300 μg/L and transferrin saturation >50%, and female patients with ferritin >200 μg/L and transferrin saturation >45%, should undergo weekly or biweekly phlebotomy, removing a blood volume of 400–500 mL, equivalent to 200–250 mg of iron, each session." (PMID 34067164, 2021). "However, the additional finding of a raised transferrin saturation increases the likelihood of hyperferritinemia being related to HFE hemochromatosis, compared to that of an isolated ferritin >1000 μg/L in Caucasians." (PMID 34067164, 2021). "Furthermore, increased saturation of transferrin and high iron in plasma (i.e. extracellular concentrations) are hallmarks of hemochromatosis forms." (PMID 31105509, 2019). "Ferroportin disease is a distinct autosomal dominant disorder, often confused with ferroportin-associated hemochromatosis, which is characterized by low transferrin saturation and tissue iron overload predominantly in non-parenchymal cells." (PMID 30420953, 2018). "In details, four genes of iron homeostasis (Hemochromatosis (HFE: C282Y, H63D), Ferroportin (FPN1: -8CG), Hepcidin (HAMP: -582AG), Transferrin (TF: P570S)), and the three major alleles of APOE (APOE2, APOE3, APOE4) were analyzed to explore causative interactions and synergies." (PMID 29518107, 2018). "However, in conditions with excess iron uptake from the gut or parenteral iron infusion, the iron-binding capacity of transferrin can be exceeded leaving to pathological deposition of iron widely in the body, a clinical condition called hemochromatosis." (PMID 26106291, 2015). "Our case emphasizes the importance of liver biopsy in helping determine the etiology of new-onset hepatitis where initial work-up has been inconclusive and dangers of relying on transferrin saturation for presumptive diagnosis of hemochromatosis pending HFE-gene testing." (PMID 24024049, 2013). "However, in the case presented herein, the transferrin saturation was 89%, strongly (but erroneously) suggesting the diagnosis of hemochromatosis." (PMID 24024049, 2013). "Elevated transferrin and serum iron (~1.2 fold higher) have been reported in OCP females, from the first to the third generation of OCP pills, with females on these OCPs more likely to have transferrin saturation levels >45% and be considered at risk of hemochromatosis." (PMID 35966107, 2022). "Strikingly, we observed that in hereditary and secondary hemochromatosis the amount of retained iron of a 59Fe radiolabeled oral test dose of only 1 mg Fe(II) that was utilized for RBC production was lower when compared to the utilization of injected 59Fe radiolabeled transferrin-bound iron." (PMID 32041196, 2020). "DMT1 may also directly transport non-transferrin-bound iron (NTBI) into cells in vivo, especially in conditions including hemochromatosis and hemolytic anemia when serum iron concentrations exceed the binding ability of transferrin, and therefore NTBI accumulates." (PMID 24982634, 2014).
hemochromatosis (continued). "Thus, in patients with altered ferritin and transferrin saturation and negative molecular analysis, all causes of secondary hemochromatosis are to be excluded, among which iron-loading anemias and viral and alcoholic chronic liver diseases." (PMID 24222913, 2013). "The diagnosis of hemochromatosis is mainly based on (i) enhanced serum ferritin levels (>300 microg/L in men and >200 micog/L in females), which correlates with the increased iron content of liver and (ii) the high transferrin saturation (>50% in males and >45% in females)." (PMID 24222913, 2013). "Because iron can enhance the oxidative effects of lead, we examined whether polymorphisms in iron metabolism genes [hemochromatosis (HFE), transferrin (TF) C2, and heme oxygenase-1 (HMOX-1)] increase susceptibility to the effects of lead on QT interval in 613 community-dwelling older men." (PMID 19165391, 2009). "Furthermore, we showed that half-life of transferrin-bound iron in patients with non-transfusion-dependent hereditary anemia is comparable with iron deficient patients but approximately half that in hereditary hemochromatosis patients." (PMID 32041196, 2020). "Five SNPs in 4 genes were assessed: hemochromatosis (HFE: C282Y, H63D), ferroportin (FPN1: -8CG), hepcidin (HEPC: -582AG), and transferrin (TF: P570S)." (PMID 22883388, 2012). "When transferrin is saturated with Fe3+ and serum iron levels are high, as in iron overload diseases such as hemochromatosis, non-transferrin-bound iron (NTBI) can also be present in plasma." (PMID 41361203, 2025). "To explore the cause of neonatal liver failure, we measured serum ferritin level, transferrin saturation, and transferrin level to rule out neonatal hemochromatosis, showing markedly elevated transferrin saturation (96.34%) and ferritin level (248.88 ng/mL)." (PMID 41300657, 2025). "Among the serum indicators, the mean values of initial ferritin, initial transferrin saturation, and last transferrin saturation were higher among patients with hemochromatosis; however, these differences were not statistically significant." (PMID 39720661, 2024). "A hemochromatosis was possible in view of a high ferritin and a transferrin saturation level > 45%, but this alone does not explain the appearance of fulminant hepatitis (a mutation of the HFE gene was not sought)." (PMID 37457563, 2023). "Iron transport via transferrin seems not to contribute significantly to continuous hepatic iron loading in hemochromatosis, because both transferrin and hepatic transferrin receptor 1 (TfR1) are downregulated under iron-overload conditions." (PMID 32041196, 2020). "Such hypohepcidinemia is expected to favor transferrin saturation increase and the appearance of NTBI that could participate in the arthritis of hemochromatosis patients." (PMID 30486249, 2018). "Thus, in appropriate clinical setting, the presence of very high transferrin saturation (>45%) is generally suggestive of primary hemochromatosis and serves as threshold to order HFE-gene testing to diagnose hemochromatosis." (PMID 24024049, 2013). "The present results suggest that the occurrence of Native American ancestry in whites would not significantly affect outcomes of hemochromatosis diagnosis and screening with transferrin saturation or serum ferritin measurements." (PMID 16533407, 2006). "However, the lack of other clinical features of hemochromatosis, normal transferrin saturation, and absence of a family history of liver disease as well as normal genetic studies, made this diagnosis unlikely." (PMID 39229407, 2024).
malnutrition (87 papers, 2012 to 2025). Inadequate nutrition resulting from poor diet, malabsorption, or abnormal nutrient distribution. "Although albumin, transferrin, and total cholesterol are dependent on several factors, low serum levels together with reduced ingestion, weight loss, and low BMI supported a malnutrition diagnosis at baseline in all of the patients." (PMID 41007653, 2025). "In assessing unfavorable outcomes after primary TKA, malnutrition (p = 0.025) and transferrin levels (p = 0.021) were associated with postoperative hospitalization time in bivariate analysis." (PMID 40727701, 2025). "Transferrin is responsible for iron transportation, and low transferrin levels are commonly associated with malnutrition, liver disease, inflammation, thyroid dysfunction, and tumors." (PMID 38539451, 2024). "Considering that the conventional iron biomarker transferrin saturation (TSAT) is susceptible to malnutrition and inflammation, we utilized serum iron as the marker of iron status in our main analysis and TSAT in the sensitivity test." (PMID 36983703, 2023). "Age > 60 years (odds ratio, OR = 6.78), neutrophil–lymphocyte ratio > 2.62 (OR = 3.862), transferrin < 200 mg/dL (OR = 4.222), phase angle < 4.5° (OR = 7.478), and body fat percentage < 10% (OR = 19.119) were risk factors for malnutrition in patients with CKD." (PMID 37299602, 2023). "Advanced age, high neutrophil–lymphocyte ratio, low transferrin level, low phase angle, and low body fat percentage are risk factors for malnutrition in patients with CKD." (PMID 37299602, 2023). "Intestinal microecological homeostasis was disrupted, and the rats exhibited signs of malnutrition, such as weight loss and decreased serum albumin and transferrin levels." (PMID 36458537, 2022). "Almost half of the patients (48.5%) were deficient in transferrin, which also indicates significant malnutrition and has been implicated in wound complications in arthroplasty." (PMID 34768533, 2021). "A recent investigation in patients on hemodialysis showed that Malnutrition Inflammation Score, composite assessment of inflammation and nutritional status including serum albumin and transferrin, is associated with the response to ESA." (PMID 33863297, 2021). "Nutritional deficiencies were found for prealbumin, albumin and transferrin at 50.5%, 23.4% and 48.5%, respectively." (PMID 34768533, 2021). "When malnutrition was defined as low transferrin, Roche et al27 identified an association with increased risk of postoperative infection (odds ratio [OR]: 1.87) and wound complications (OR: 1.9)." (PMID 33939393, 2020). "Based on this systematic review, sufficient evidence is not available to make a statement regarding the risk for postoperative complications in patients with malnutrition as defined by low transferrin or low TLC." (PMID 33939393, 2020). "More than 44% individuals of the study population was at risk of malnutrition, according to feeding difficulties, progressive depletion of weight, reduced daily calorie intake, reduced albumin and transferrin levels." (PMID 25000975, 2014). "Notably, the FT3/FT4 ratio demonstrated an independent association with nutritional status, as well as with transferrin and albumin levels, which are critical biomarkers of malnutrition and impaired hepatic function." (PMID 40725539, 2025). "Some factors that may contribute to the lack of blood pressure control in patients with CKD include hypervolemia, malnutrition, excess transferrin saturation, and arteriolopathy, which can cause peripheral ischemia (vascular amputation)." (PMID 39825259, 2025). "However, a contradictory opinion suggests that biochemical parameters like transferrin, hemoglobin, prealbumin and serum creatinine etc., when used solely, are insensitive diagnostic markers of malnutrition." (PMID 38712760, 2024).